IL2 (interleukin 2)
Diseases named in the same sentence as IL2 in open-access papers (continued):
Sharing a sentence is not in itself a finding about the gene and the disease.
tumor (continued). "Furthermore, animals receiving the TSCM-like CD4+ T cells had significantly delayed tumor growth compared to mice receiving the same number of T cells expanded in IL-2." (PMID 37400675, 2023). "Reducing miR-15/16 expression might be beneficial in cancer immunotherapies where decreased IL-2 sensitivity in Tregs could limit IL-2-induced Treg amplification while maintaining IL-2 responsiveness in tumor-infiltrating lymphocytes." (PMID 37862171, 2023). "However, only conditions containing T-cell activating beads, IL-2 or IL-15 showed statistically significant 624-MEL-GFP tumor spheroid killing." (PMID 37923822, 2023). "The results showed that rAd-IL-2 significantly stimulated tumor-specific cytotoxic T lymphocyte responses by inducing the recruitment of CD4+ and CD8+ T cells to tumors, leading to tumor regression and long-term survival of mice during the 120-day treatment period." (PMID 37234162, 2023). "Then, the levels of IL‐2 from tumor homogenates were measured over 9 days." (PMID 36684086, 2023). "Reshaping the chemistry of IL-2 interface with the IL-2R beta chain served both purposes and provided a panel of IL-2R super-agonists able to enhance immune effector functions and anti-tumour activity." (PMID 37558752, 2023). "Results showed that CPG administration of 100 mg/kg could effectively inhibit tumor growth in mice with an inhibitory ratio of 45.37% and significantly improve the expression of Interleukin-2 (IL-2), Interferon-γ (IFN-γ), and Tumor Necrosis Factor-α (TNF-α)." (PMID 37958581, 2023). "Combined IL-2 therapy with PD1/PDL1 blockade showed more powerful anti-tumor responses." (PMID 37398660, 2023). "Indeed, treatments of metastatic RCC with exogenously administered TNF-α and IL-2 were among the first anti-tumor immune therapies that were FDA-approved." (PMID 37568390, 2023). "IL-2 is a pro-inflammatory cytokine, doted of the anti-tumor response." (PMID 36835413, 2023). "Consistent with the enhanced CTL expansion, the proinflammatory cytokines interleukin‐2 (Il‐2), tumor necrosis factor (Tnf)‐α, and interferon (Ifn)‐γ, which promote antitumor immune response, were found significantly enhanced in tumor tissues after G4 treatment." (PMID 37222047, 2023). "Indeed, at the early course of tumor growth, IL-2-mediated induction of BLIMP1 expression is required for effector CD8+T cells growth and differentiation." (PMID 37106742, 2023). "IL-2 is a critical factor for T cell proliferation, survival, and immune function, while the binding of PD-L1/PD-1 induces CD8+ T cell apoptosis and loss of anti-tumor function." (PMID 38299141, 2023). "However, IL-2/IL-2R signaling can also promote Treg expansion, potentially inhibiting the anti-tumor immune response." (PMID 37516849, 2023). "Hence, maintaining the balance between IL-2 and IL-2R signaling is critical for effective anti-tumor immunity." (PMID 37516849, 2023). "Immunization with engineered tumor cells also leads to the production of IL-2." (PMID 38140187, 2023). "We demonstrate the approach with a previously designed mimetic of cytokines interleukin-2 and interleukin-15—Neoleukin-2/15 (Neo-2/15)—both for trans-activating immune cells surrounding targeted tumor cells and for cis-activating directly targeted immune cells." (PMID 36316485, 2023). "Thus, IL12-MSA was able to reduce the Treg frequency in tumor-bearing lungs even in the presence of IL2-MSA, despite concomitant expansion of Tregs in secondary lymphoid tissues during combination treatment." (PMID 37669107, 2023). "For instance, IL-2/IL-2R signaling may promote the expansion of Tregs, which could potentially inhibit anti-tumor immune responses, thereby facilitating tumor growth." (PMID 37516849, 2023). "Besides, Noor Momin and colleagues reported two fusion proteins of collagen-binding protein lumican with IL-2 and IL-12, which represented impressive anti-tumor efficacy when administrated individually or jointly in multiple mouse models." (PMID 37692860, 2023).
tumor (continued). "In vivo, it was found that ADP could increase the content of IL-2 in the serum of H22 tumor-bearing mice." (PMID 37959774, 2023). "TIL therapy is based on the extraction of tumor-infiltrating lymphocytes for ex vivo expansion and reinfusion to the patient, after lymphodepleting conditioning, in combination with immune-enhancing adjuvants such as IL-2." (PMID 37190214, 2023). "Also, the use of DSP30 and IL‐2 mitotic stimuli at low levels of neoplasia (less than 10%) increases the ability to diagnose abnormalities, while the lipopolysaccharide (LPS) stimulator does not have this ability at a low level." (PMID 36411516, 2023). "Interestingly, when the tumor size was reduced by the IL-2 drug, the number of immune cells infiltrated into the tumor was significantly increased." (PMID 37711172, 2023). "Indeed, treatments with IL-2 mutant proteins reduced the number of Tregs and inhibited tumor growth." (PMID 37671150, 2023). "IL-2 treatment ceased, and one year after surgery, the dog was still tumor-free." (PMID 36765608, 2023). "Moreover, IL2 enhanced the sensitivity of NK cells to apoptosis when they came into contact with vascular endothelium, leading to a reduction in tumor NK cell infiltration." (PMID 37190251, 2023). "To determine whether IL2-REH-MSA could prevent the activation of non-tumor-specific CD8+ T cells, we compared IL12-MSA binding by SIY-nonreactive CD8+ T cells from mice treated with either IL2-MSA or IL2-REH-MSA." (PMID 37669107, 2023). "In addition, FDX1 overexpression restrained ccRCC cell line malignancy and enhanced tumor immunity by increasing the secretion levels of IL2 and TNFγ." (PMID 36766692, 2023). "Therefore, the combination of IL12-MSA and IL2-MSA is effective at promoting increased tumor control while inducing significant dose-limiting toxicity." (PMID 37669107, 2023). "This may explain why immune-excluded tumor models are still resistant to CAR T cells with constitutive IL-2 expression, even though it is also autocrine." (PMID 37308558, 2023). "Depletion of CD4+ T cells even more improved the anti-tumor effect of Dox plus IL-2ic combinational treatment, presumably due to the depletion of Tregs, which could still limit IL-2 availability between the IL-2ic injections." (PMID 36705564, 2023). "Thus, following the isolation of tumour-infiltrating lymphocytes from biopsy samples and subsequent ex vivo expansion using IL-2, TILs are infused into a patient who has undergone lymphodepletion." (PMID 36765809, 2023). "Adoptive cell therapy (ACT) is an antitumor therapy in which autologous immune cells are activated in vitro by interleukin-2 (IL-2) as well as other cytokines, amplified to a certain number, and then injected back into the body of cancer patients where they can kill tumor cells in vivo." (PMID 36908706, 2023). "GHCer could be transferred from cancer cells into non-tumor cells located in the tumor microenvironment, such as endothelial cells, promoting angiogenesis, as well as into T cells, inhibiting IL-2, interferon-γ, and IL-4 secretion, promoting immunosuppression." (PMID 38203654, 2023). "For example, IL-2 gene therapy can be used to deliver IL-2 directly to tumor cells, which may enhance T cell activation and proliferation in the tumor micro-environment." (PMID 37516849, 2023). "Our results suggest that the addition of IL-2 and IL-12 or their combination may shift the balance in favour of tumour eradication." (PMID 37629081, 2023). "We found increased release of IL-2 in tumor-infiltrated CD8+ T cells by RGE treatment." (PMID 36768213, 2023). "Moreover, IL-2 signaling blockade enhanced the anti-tumor immune response and inhibited tumor growth in murine models." (PMID 37516849, 2023). "The role of IL-2 in enhancing anti-tumor activity is well established." (PMID 36992219, 2023).
tumor (continued). "However, these CAR-T cells were unsuccessful in targeting TAAs on tumour cells, due to their inability to produce IL-2 to promote their proliferation and expansion of numbers." (PMID 39935547, 2023). "Analyzing the subsets of these factors highly expressed by PV001-DV’s infection of PBMCs, several of the known tumor apoptosis-inducing factors such as TNF-a, IL-12p70, are observed to overcome tumor evasion mechanisms, and IL-2 is observed to be synergistic with anti-CTLA-4 therapy." (PMID 37468934, 2023). "Andrographolide decreased tumor-specific angiogenesis by lowering the manufacture of the pro- and anti-angiogenic factors such as interleukin-2, vascular endothelial growth factor, nitric oxide, and tumor necrosis factor TNF-α, in the C57BL/6 mice infected with the B16F-10 melanoma cells." (PMID 37653887, 2023). "The current status of clinical testing indicates that in-depth preclinical investigations of IL-2-based drugs alone and in combination with other treatments are extremely important for further clinical development, both with regard to anti-tumor effects and with regard to mechanistic aspects." (PMID 37045833, 2023). "IL-2 is an important cellular immune factor with anti-tumor effects." (PMID 37256111, 2023). "Moreover, CD4+ T lymphocytes exhibited direct eradication ability of tumor cells by IL2 neutralization 36 which makes targeting CD4+ T lymphocytes a promising therapy for HL-related ICC." (PMID 37215452, 2023). "SUMO-C1 corresponded to a tumor immunoinflammatory phenotype with better overall survival, significant activation of immune pathways such as the IL2, inflammatory, complement, and allograft rejection pathway, and increased infiltration levels of anti-tumor immune cells." (PMID 37123398, 2023). "Therefore, this review article aims to delineate the dichotomy of IL-2 and IL-2R’s functions within the tumor milieu and its implications for cancer immunotherapy." (PMID 37516849, 2023). "Therefore, its reduction led to increased T cell activation with IL-2 cytokine production and subsequent suppression of tumor immune escape by inhibiting PD-1/PD-L1 pathway." (PMID 37563607, 2023). "This led the authors to speculate that differences in the microbiome affect the glycerophospholipid metabolism, which alters IFN-γ and IL-2 expression in the tumor microenvironment, resulting in better anti-PD-1 response." (PMID 38035338, 2023). "OV-induced tumor immunity can be enhanced by the delivery of anti-tumor cytokines, such as IFNα, TNFα, IL-2, IL-12, and GM-CSF, while tumor-targeted cytokine delivery avoids the significant toxicity associated with systemic delivery while also boosting the immune response." (PMID 38203382, 2023). "In addition, IL-2 promotes autocrine survival and cytolytic activity of T and NK cells in anti-tumor immunity." (PMID 36835413, 2023). "In addition, WGP promoted the increase of Th1-type cytokines IFN-γ and IL-2 and the decrease of Th2-type cytokines IL-4 and IL-10, which can induce the differentiation of T cells, further demonstrated its anti-tumor ability." (PMID 36713833, 2023). "However, only PEPT CAR-T cells displayed lower levels of IFN-γ, TNF-α, and IL-2 release compared to 2G CAR-T cells when challenged with CD19 + PDL1- tumor cells." (PMID 37777797, 2023). "Furthermore, growing PD-1+ Treg cells can take up IL-2 and remove IL-2 from tumor-reactive effector T cells, leading to insufficient IL-2 required for effector T cell activation, further reducing effector T cell functions." (PMID 36831655, 2023). "Autologous-TILs were expanded ex-vivo from minced tumor tissue and cultured with IL-2." (PMID 38067208, 2023). "In addition, IL-2 can further induce the expansion of NK cells, which increases tumor-specific cytotoxicity." (PMID 37516849, 2023). "The combination of IL-2 with PD-1 pathway blockade can exert synergistic effects, and it may be an attractive strategy for tumor immunotherapy." (PMID 36891319, 2023).
tumor (continued). "IL-2 could promote the tumor-specific NK cells and T cells activities, and IL-4 could regulate immune responses." (PMID 37764221, 2023). "Consistent with these previous findings, the AFP TCR T cells with c-Jun overexpression from the tumor mass were less exhausted and less apoptotic and were better able to maintain their function of killing target tumor cells and producing more cytokines of IL2 and IFNγ." (PMID 37215108, 2023). "Besides, down-regulation of PTPRC lead down-regulation of tumor-derived IL2 and up-regulation of tumoral PD-L1." (PMID 37388747, 2023). "In vivo experiments on mouse model confirmed that growth factors in healing wounds may promote tumor growth, affecting therapeutic effect of immunotherapy with interleukin-2 (IL-2) and lympokine activated killer (LAK) cells." (PMID 37161562, 2023). "Furthermore, IL-2 activated NK cells that undergo apoptosis upon initial interaction with endothelial and tumor cells, while IL-15 maintains NK cell survival under the same condition." (PMID 38106519, 2023). "Once tumor volumes reached 200–300 mm3, human T cells transduced with GD2_tTF, GD2_tTFmut or CD19_tTF were intraperitoneally (i.p.)administered on days 1 and 4, along with human interleukin-2." (PMID 37391502, 2023). "To determine whether CoStAR could mitigate this IL-2 dependence we performed an in vitro model of serial stimulation to mimic repeated tumor engagement." (PMID 38022678, 2023). "Given this fact and the central role of DCs in generating anti-tumor immune responses, we aimed to evaluate if the new virus LOAd732, which additionally expresses IL-2, could still activate immature DCs." (PMID 37501121, 2023). "Currently, little is known about how effectively triple combinations containing an IL-2 derivative expand tumor-specific T cells, and what effects they have on subsets of dysfunctional/exhausted T cells in different compartments relevant to the antitumor T cell response." (PMID 37045833, 2023). "Furthermore, APS can upregulate the levels of IL-2 in the serum of 4T1 tumor-bearing mice and H22 hepatoma mice and promote the levels of IL-4 and IL-10 in the serum of tumor-bearing mice treated with a focused ultrasound." (PMID 37959774, 2023). "Furthermore, TRuC T cells secreted IL-2 upon co-stimulation with tumor cells and IL-2 secretion was higher in MSLN-TRuC T cells co-expressing the PD-1-CD28." (PMID 36409438, 2023). "Therefore, after the cells were co-cultured with tumor cells for 24 h, we simultaneously investigated the secretion potential of IL-2 and IFN-γ by our engineered T cells in each group using ELISA." (PMID 37670338, 2023). "Previous research has indicated that high PD-L1 expression can inhibit the function of Jurkat cells, leading to a reduction in IL-2 expression.Consistent with the mentioned study, we observed a decrease in IL-2 levels in the co-culture medium containing tumor cells." (PMID 38299141, 2023). "IL-2 monotherapy significantly suppressed tumor growth and prolonged survival." (PMID 37398660, 2023). "Wild-type IL-2 administration for cancer receives low complete response rates and poor tumor control due to its short half-life, which requires a very high amount of intravenous IL-2 associated with severe non-specific toxicities, and off-target effects on Treg cells." (PMID 38049832, 2023). "We here describe a potency-matched dual-cytokine antibody fusion protein containing a tumor-targeting antibody fragment specific to human fibroblast activation protein (FAP), simultaneously linked to both interleukin-2 (IL2) and a tumor necrosis factor (TNF) mutant." (PMID 37092450, 2023). "Indeed, cytokines such as IFN-γ, IL-27, IL-23, IL-12, and IL-2 have tumor suppressor functions, whereas pro-inflammatory cytokines, including IL-1, IL-6, and tumor necrosis factor-α, have tumor-promoting." (PMID 37046658, 2023).
tumor (continued). "Not so long ago, a series of studies lead by Dr. Rosenberg opened a new field by proposing to re-infuse in vitro expanded and IL-2-stimulated tumor-infiltrating lymphocytes to overcome immunotolerance in patients with metastatic melanoma and achieve tumour-control." (PMID 38187393, 2023). "Our findings that FAP is expressed on the NK cell surface suggests that anti-FAP/IL-2 fusion protein may also target IL-2 directly to NK cells, enhancing NK cell activation and potentially tumor clearance." (PMID 38196606, 2023). "CMPs could increase the serum levels of IFN-γ and IL-2, act on the spleens and thymuses of mice, and improve the immune activity of the tumor-bearing mice." (PMID 37960180, 2023). "Therefore, IL-2 has been used in combination with other immunotherapies, such as checkpoint inhibitors, to optimize anti-tumor immune responses." (PMID 37516849, 2023). "Besides, CD4+ T cells can secret multiple cytokines to mediate anti-tumor effects, for instance, the secretion of IL-2 from Th1 cells is essential for the function of CD8+ T cells such as the initiation of the immune response and its growth." (PMID 37287989, 2023). "IL-2 restores Fbxo38 transcription and promotes PD-l degradation in tumor infiltrating T cells." (PMID 36733484, 2023). "Restimulation of peripheral blood mononuclear cells (PBMCs) from AU-011 PDT treated animals with irradiated TC-1 cells ex vivo showed enhanced secretion of IFN-y with IL-2 and TNF-a with IL-2 compared to the relevant controls, indicating the existence of activated tumor specific lymphocytes." (PMID 36997666, 2023). "IL-2, IL-15, and IL-21 in the IL-2 cytokine family play a positive role in anti-tumor effects, and IL-4, IL-7 and IL-9 possess pleiotropic functions, with diverse roles in cancer immunity as they can have pro-tumorigenic functions as well as anti-tumorigenic characteristics." (PMID 36936961, 2023). "IL2-MSA led to a significantly increased Treg fraction in the spleens of KP.SIY tumor-bearing mice." (PMID 37669107, 2023). "Indeed, IL-2/JES6 in combination with chemotherapy significantly prolonged the survival of tumor-bearing mice in two different tumor models in a CD8+ T-cell-dependent manner." (PMID 36705564, 2023). "Moreover, blockade of inhibitory KIR with IL-2 triggering reversed the functional hypoactivity of tumor-derived NK cells in GBM." (PMID 37762486, 2023). "One mechanism of action exploited by immunotherapy is the activation or re-activation of cytotoxic T lymphocytes against cancer cells through the administration of tumor vaccines, cytokines such as interleukin-2, or through the adoptive transfer of tumor-infiltrating T cells (TILs)." (PMID 37111737, 2023). "IL-2 rapidly proliferates lymphocytes that kill tumour cells, although at low abundance." (PMID 36765809, 2023). "Additionally, IL-2 can mediate the proliferation and activation of natural killer (NK) cells, enhancing their tumor lytic capabilities." (PMID 38259287, 2023). "For example, stimulation with IL-2, IL-7, IL-15, and IL-21 promoted the enrichment and proliferation of tumor antigen-specific TSCM, which exhibited more distinct heterogeneous differentiation and self-renewal potential than did the original TSCM isolated in vivo." (PMID 36891319, 2023). "Infiltrated immune cells shift their phenotypes from anti-tumor, also known as pro-inflammatory phenotypes, to pro-tumor phenotypes because tumor cells increase interleukins and chemokines such as IL-2, IL-4, IL-6, IL-7, IL-10, IL-12, and CXCL12 concentrations." (PMID 37533070, 2023). "Ex vivo expansion of NK cells from cancer patients possessed excellent tumor-killing ability in PDX under the administration of IL-2 injection to maintain cell viability, providing a promising path to reconstitute the patients’ exhausted immune function compatible with existing immunotherapies." (PMID 37045827, 2023).